SLFN11 (schlafen family member 11)
Diseases named in the same sentence as SLFN11 in open-access papers (continued):
Sharing a sentence is not in itself a finding about the gene and the disease.
ovarian carcinoma (continued). "High SLFN11 expression independently predicted OS in a group of ovarian cancer patients treated with cisplatin-containing regimens." (PMID 26525741, 2015). "SLFN11 expression reportedly predicts independently overall survival (OS) in ovarian cancer patients treated with cisplatin-based regimens." (PMID 26525741, 2015). "In BRCA wild - type ovarian cancer, determine whether SLFN11 can serve as an independent predictive marker for the efficacy of olaparib to compensate for the limitations of homologous recombination deficiency (HRD) testing." (PMID 40766331, 2025). "Unmethylated SLFN11 has also been found to stably suppress colorectal cancer proliferation and sensitize colorectal cancer cells to cisplatin treatment, as in the case of ovarian cancer cells as well." (PMID 41303540, 2025). "Besides, the quantification of SLFN11 either by transcript levels or immunohistochemical assessment revealed a broad range of SLFN11 expression in various tumor types, including ovarian cancer." (PMID 35625957, 2022). "We review the available information about the prevalence of SLFN11 in ovarian cancer, the possibilities of its determination in tumor tissue, as well as the current level of evidence about the correlation between SLFN11 expression levels in ovarian cancer and response to DDA or PARPi." (PMID 35625957, 2022). "In this review, we aim to summarize the current knowledge of the role of SLFN11 in ovarian cancer." (PMID 35625957, 2022). "Our results strongly indicate that SLFN11 epigenetic inactivation could be a predictor of resistance to platinum drugs in ovarian cancer." (PMID 35008168, 2021). "Others have shown the absence of SLFN11 expression due to CpG promoter island hypermethylation in ovarian cancers linked to reduced OS in patients treated with cisplatin and carboplatin." (PMID 34663950, 2021). "Our results strongly indicate that SLFN11 epigenetic inactivation could serve as a potential prognostic DNA methylation biomarker and a predictor of resistance to platinum-based chemotherapy in ovarian cancer." (PMID 35008168, 2021). "In the first study aiming to provide a comprehensive analysis of the clinical significance of SLFN11 as a predictive biomarker to DDA on a wide range of cancer models, including ovarian cancer, the cutoff of 31 H-score showed a good predictive power." (PMID 35625957, 2022). "Investigate how SLFN11 affects the response to immunotherapy by regulating immune cell infiltration (such as T cells and macrophages) or cytokine secretion (such as the CCL2/CCR2 axis), especially in hepatocellular carcinoma and ovarian cancer." (PMID 40766331, 2025). "This is further substantiated by the negative correlation of SLFN11 immunohistochemical staining with cisplatin treatment response in ovarian cancer." (PMID 38001424, 2023). "High SLFN11 associated with improved prognosis to the first-line treatment with DDAs platinum-plus-etoposide in SCLC patients, but was not strongly linked to paclitaxel–platinum response in ovarian cancer patients." (PMID 34663950, 2021). "Our findings suggest high levels of SLFN11 may confer sensitivity to olaparib in platinum-sensitive ovarian cancer patients, but will not replace BRCAm as a key driver of sensitivity." (PMID 34663950, 2021).
colorectal cancer (14 papers, 2015 to 2025). A primary or metastatic malignant neoplasm that affects the colon or rectum. "Colorectal carcinomas with diffuse SLFN11 positivity were often mismatch repair deficient tumors with their typical clinical, morphological, and molecular characteristics." (PMID 40105034, 2025). "Beyond its antiviral capabilities, emerging research highlights SLFN11’s role in enhancing cancer cell sensitivity to DDAs, making it a potential biomarker for predicting treatment outcomes in ovarian, lung, and colorectal cancers." (PMID 40740189, 2025). "Another study that examined SLFN11 in colorectal cancer patients’ samples recorded SLFN11 to be methylated in 55.47% (71/128) of the colorectal cancer patient samples." (PMID 41303540, 2025). "The expression level of SLFN11 is a key determinant regulating the sensitivity of colorectal cancer (CRC) cells to DNA-damaging chemotherapeutic drugs." (PMID 40766331, 2025). "SLFN11 profoundly affects the response of colorectal cancer (CRC) to DNA-damaging chemotherapy drugs, including irinotecan and platinum (oxaliplatin, cisplatin), by participating in the DNA damage response pathway." (PMID 40766331, 2025). "We observed that the synergy for the gefitinib/SN-38 combination in SLFN11 positive colorectal cancer cells is correlated with the ABCG2 expression." (PMID 39033209, 2024). "Our study aimed to investigate the significance of redox status parameters, and the SLFN11 and PD-L1 proteins, as well as their combined effect as prognostic biomarkers in patients with colorectal cancer." (PMID 37894765, 2023). "Thereby, SLFN11 functions as a tumor suppressor in colorectal cancer, and its methylation status may indicate cisplatin resistance." (PMID 41303540, 2025). "SLFN11 has been studied in different types of cancer including colorectal carcinomas." (PMID 40105034, 2025). "SLFN11 and PD-L1 have been chosen since they have been in the limelight of colorectal cancer research in recent years, with an essential role as immunological checkpoints and potential therapeutical targets as well as biomarkers for response and prediction of therapy outcomes." (PMID 37894765, 2023). "The study was to investigate whether SLFN11 expression is related to sensitivity to adjuvant oxaliplatin-based treatment in colorectal cancer." (PMID 26525741, 2015). "A range of SLFN11 expression in colorectal cancer (CRC) has been observed." (PMID 26525741, 2015). "Interestingly, SLFN11 sensitizes RKO, DLD1, and SW620 colorectal cancer cells to cisplatin and reduces in vivo tumor growth in mice, suggesting a favorable role for SLFN11 in CRC." (PMID 34571887, 2021).
hepatocellular carcinoma (14 papers, 2020 to 2025). A malignant tumor that arises from hepatocytes. "Tumor-specific deficiency of SLFN11 enhanced the infiltration of Suppressive macrophages and exacerbated the progress of hepatocellular carcinoma (HCC)." (PMID 39558948, 2024). "A study on hepatocellular carcinoma found that SLFN11 deficiency can enhance the infiltration of immunosuppressive macrophages and promote their transformation to the M2-like phenotype by activating the Ccl2 signaling pathway, thereby exacerbating tumor progression." (PMID 41562082, 2025). "A study has shown that SLFN11 can act as a tumor suppressor by suppressing the mTOR pathway by targeting RPS4X in hepatocellular carcinoma, which suggests that its mutation may lead to the loss of its inhibitory effect on mTOR." (PMID 37189093, 2023). "Furthermore, SLFN11 suppresses the proliferation of hepatocellular cancer cells by interacting with the ribosomal protein S4 X-linked (RPS4X), resulting in attenuation of S6 and eIF4E phosphorylation in the ribosome complex and inhibition of the mTOR signaling pathway." (PMID 35768579, 2022). "By contrast, in hepatocellular carcinoma (HCC) patients, decreased expression of SLFN11 was linked to worse overall survival and increased recurrence." (PMID 38791884, 2024). "Rather than a by‐effect of an IFN‐γ‐rich milieu, SLFN11 itself actively regulated the immune landscape and was associated with the efficacy of anti‐PD‐1 therapy in hepatocellular carcinoma." (PMID 40105034, 2025). "Recent studies have strongly suggested that SLFN11 is a key regulator in the immune microenvironment of hepatocellular carcinoma (HCC) and shows great potential as a biomarker for predicting the efficacy of immune checkpoint inhibitors (ICI) treatment." (PMID 40766331, 2025). "In hepatocellular carcinoma, RPS4X is required for SLFN11 inactivation in the mTOR signaling pathway." (PMID 36474171, 2022). "In addition to its replication stress checkpoint functions, SLFN11 interacts with ribosomal protein S4 X-linked (RPS4X) and suppresses the mTOR signaling pathway in hepatocellular carcinoma (HCC), inhibiting HCC growth and metastasis." (PMID 35768579, 2022). "SLFN11 mRNA and protein are downregulated in hepatocellular carcinoma (HCC) vs. non-tumor liver tissues." (PMID 34571887, 2021).
gastric cancer (10 papers, 2019 to 2025). A primary or metastatic malignant neoplasm involving the stomach. "In the gastric cancer cohort, it was indicated that expression of Schlafen family genes, among others, SLFN11, was positively associated with infiltration of numerous immune cells, including CD4+ T cells and CD8+ T cells." (PMID 40649874, 2025). "Conversely, long-term oxaliplatin treatment in both gastric carcinoma cells and organoids reduces SLFN11 expression, causing oxaliplatin resistance that is reversed by reactivation of SLFN11 (with epigenetic modifying drugs)." (PMID 34571887, 2021). "Furthermore, in vitro knockout and reactivation of SLFN11 in gastric carcinoma cell lines (MKN-1, MKN-7, MKN-45, and MKN-74) causes resistance and sensitivity to platinum-based chemotherapy, respectively." (PMID 34571887, 2021). "Compared to normal gastric mucosal tissues, SLFN11 gene methylation is more prevalent in gastric cancer tissues, and the methylation rate of SLFN11 was significantly higher in tumors with a diameter ≥5 cm than in tumors with a diameter <5 cm." (PMID 40766331, 2025). "SLFN11 can enhance the sensitivity of gastric cancer cells to cisplatin by promoting cisplatin-induced S-phase arrest and apoptosis." (PMID 40766331, 2025). "High expression of SLFN11 can be used as a predictive biomarker for gastric cancer patients receiving platinum-based chemotherapy." (PMID 40766331, 2025). "Kaplan-Meier analysis showed that the 5-year overall survival rates of 169 gastric cancer patients were 63% and 40% in the high SLFN11 group and the low SLFN11 group, respectively." (PMID 40766331, 2025). "Restoring SLFN11 expression significantly inhibits the proliferative capacity of gastric cancer cells (such as SNU16 and MGC803)." (PMID 40766331, 2025). "SLFN11 suppressed gastric cancer growth both in vitro and in vivo, which suggested an enhanced ability of cisplatin to induce S-phase arrest and apoptosis in gastric cancer cells." (PMID 41303540, 2025). "At the epigenetic level, SLFN11 is frequently methylated in gastric cancer and its expression is regulated by promoter region methylation." (PMID 40766331, 2025). "In a study on gastric cancer, 169 patients with advanced gastric cancer were analyzed for SLFN‐11 expression based on IHC." (PMID 39809728, 2025). "The TCGA database showed that the mRNA expression of SLFN11 in gastric cancer (STAD) was significantly higher than that in normal tissues." (PMID 40766331, 2025). "For instance, SLFN11 has been shown to suppress gastric cancer growth both in vitro and in vivo and to enhance the capacity of cisplatin to induce S-phrase arrest and apoptosis in gastric cancer." (PMID 36035159, 2022). "SLFN11 expression as a prognostic biomarker has also been confirmed in esophageal and gastric cancers after chemoradiotherapy, showing a positive correlation." (PMID 34572827, 2021). "Gastric cancer patients with lower tumor classification and stage show high SLFN11 expression, exhibiting better survival rate after platinum-based chemotherapy." (PMID 34572827, 2021). "SLFN11 suppressed gastric cancer growth both in vitro and in vivo and enhanced the ability of cisplatin to induce S-phrase arrest and apoptosis in gastric cancer cells." (PMID 31762822, 2019). "SLFN11 is often methylated in human stomach cancer, and experimental findings demonstrated that SLFN11 functions as a tumor suppressor in human gastric cancer, and that methylation of SLFN11 may act as a marker for cisplatin resistance in stomach cancer cells." (PMID 41303540, 2025). "As for gastric cancer, SLFN11 expression could be a prognostic marker for gastric and colon cancers." (PMID 34571887, 2021). "In contrast to the apparent adverse roles of SLFN5 and SLFN12L in gastric cancer, analysis of gastric carcinomas from 169 patients suggested that high SLFN11 expression correlates with better survival, which improves when patients are treated with platinum-chemotherapy." (PMID 34571887, 2021).
gastric cancer (continued). "This study explored the epigenetic regulation and mechanism of SLFN11 in human gastric cancer." (PMID 31762822, 2019). "Our results demonstrate that SLFN11 is a tumor suppressor in human gastric cancer, and methylation of SLFN11 may serve as a cisplatin resistant marker in human gastric cancer." (PMID 31762822, 2019).
leukemia (9 papers, 2016 to 2025). A malignant (clonal) hematologic disorder, involving hematopoietic stem cells and characterized by the presence of primitive or atypical myeloid or lymphoid cells in the bone marrow and the blood. "Finally, in our vitro study, we investigated the association between SLFN11 expression and sensitivity to these anticancer agents using leukemia cell lines, as in our previous report, to allow timely reporting." (PMID 33218331, 2020). "The result shows that LINE-1 repeats in chromatin are more accessible in SLFN11-KO cells compared to leukemia CCRF-CEM SLFN11-positive cells, reflecting the H3K9me3-dependent chromatin tightening required for drug-tolerant cancer cell survival." (PMID 40497966, 2025). "We generated stable cells expressing (over 80%) wild-type or mutant SLFN11 in K562 human leukemia cells, which normally have undetectable levels of endogenous SLFN11." (PMID 38125019, 2023). "We next compared the effect of the topoisomerase I (TOP1) inhibitor camptothecin (CPT) on ATAC-seq patterns in human leukemia CCRF-CEM (SLFN11-positive) cells and their isogenic SFLN11-knockout." (PMID 32321568, 2020). "Conversely, exogenous expression of SLFN11 in leukemia K562 cells that have very low SLFN11 transcript conferred hypersensitivity to talazoparib and olaparib." (PMID 27708213, 2016). "In leukemia K562 and fibrosarcoma HT1080 cell lines, both of which have a very low basal SLFN11 expression, HDAC inhibitors (romidepsin and entinostat) increase SLFN11 expression and enhance sensitivity to DNA-damaging agents in SLFN11-dependent manner." (PMID 33513156, 2021).
lung carcinoma (8 papers, 2016 to 2021). "High SLFN11 expression is also associated with a favorable outcome in lung cancers, perhaps at least in part because it sensitizes lung cancer to specific cytotoxic drugs such as DNA alkylating agents and PARP inhibitors." (PMID 32987632, 2020). "One example of how these and related approaches have altered our approach to the treatment of lung cancer patients is the discovery of SLFN11 as a biomarker of response to PARP inhibition in SCLC." (PMID 30791396, 2019). "Of these, only IGFBP3 and SLFN11 were additionally tested in clinical tissue samples derived from NSCLC patients but still showed a rather poor predictive power in lung cancer." (PMID 30029672, 2018). "Notably, promoter hypermethylation of SLFN11, which is a key source for SLFN11 inactivation, also predicts worse drug-response in platinum-based chemotherapy in ovarian or lung cancer patients, as well as a poor clinical outcome biomarker." (PMID 34572827, 2021). "High expression of either SLFN5 or SLFN11 has been reported to be prognostically favorable for lung cancer, and SLFN11 in particular has also been reported to sensitize lung cancer cells to DNA alkylating agents and poly ADP ribose polymerase (PARP) inhibitors." (PMID 32987632, 2020). "Although not examined in lung cancer cells, increasing SLFN11 expression in CD47 knockout Jurkat cells restored their radiosensitivity." (PMID 34571887, 2021). "Similarly, when analyzing only lung cancer patients who received adjuvant chemotherapy (drugs not specified), there was a significant OS benefit in patients with high SLFN11 expression in one dataset (HR = 3.72, p = 0.031) and a trend towards benefit in a second dataset (HR = 2.29, p = 0.057)." (PMID 31682620, 2019).
non-small cell lung carcinoma (8 papers, 2016 to 2025). A group of at least three distinct histological types of lung cancer, including non-small cell squamous cell carcinoma, adenocarcinoma, and large cell carcinoma. "SLFN11 was found to be significantly overexpressed, even more so than in non-small cell lung cancer, making it a potential biomarker for predicting response to PARP inhibitors in SCLC." (PMID 40224185, 2025). "Research on SLFN11 has also extended to non-small cell lung cancer (NSCLC)." (PMID 40766331, 2025). "Most importantly, we have been able to extend these findings clinically, following the observation that those patients with ovarian and non-small cell lung cancer carrying SLFN11 hypermethylation had a poor response to both cisplatin and carboplatin treatments." (PMID 26625211, 2016).
serous ovarian cancer (7 papers, 2021 to 2025). "SLFN11 expression was generally low in serous ovarian cancer samples, median H-score 20, 16% positivity (n = 151)." (PMID 34663950, 2021). "SLFN11 promoter methylation leads to decreased expression, which is significantly associated with shortened progression-free survival (PFS) and overall survival (OS) in patients with serous ovarian cancer, further confirming the key role of SLFN11 expression level in prognosis." (PMID 40766331, 2025). "In high-grade serous ovarian cancer (HGSOC), SLFN11 expression was found to be highly present in macrophages and monocytes, while in neutrophils, SLFN11 expression was barely detected." (PMID 38791884, 2024). "In the present study, we examined the methylation status of six gene promoters (BRCA1, CST6, MGMT, RASSF10, SLFN11 and USP44) in high-grade serous ovarian cancer (HGSOC)." (PMID 35008168, 2021). "By analyzing a cohort of high-grade serous ovarian carcinoma (HGSOC) specimens before platinum-based chemotherapy treatment, we show, for the first time to our knowledge, that SLFN11 density in both the neoplastic and microenvironmental components was independently associated with favorable outcome." (PMID 34549724, 2021).
sarcoma (5 papers, 2016 to 2025). A usually aggressive malignant neoplasm of the soft tissue or bone. "In these sarcomas, elevated SLFN11 protein expression was associated with worse outcome in terms of recurrence-free survival, and recurrent and resistant sarcomas still exhibited high SLFN11 expression." (PMID 36382088, 2022). "SLFN11 is highly expressed in additional types of pediatric sarcomas, including osteosarcoma, embryonal rhabdomyosarcoma, and desmoplastic small round cell tumor." (PMID 37599787, 2023). "A recent study investigated the molecular profiling of ped/AYA sarcomas and noted alterations in several DDR genes, including SLFN11, EWSR1, BRCA1, BRCA2, and MLH1." (PMID 40563612, 2025).
esophageal cancer (4 papers, 2020 to 2025). A primary or metastatic malignant neoplasm involving the esophagus. "Esophageal cancer patients who receive chemotherapy with nedaplatin and 5-fluorouracil and have high SLFN11 expression show a significantly longer overall survival than patients whose tumors express low SLFN11." (PMID 34572827, 2021). "Although this has not been investigated in vitro in esophageal cancer cells, the SLFN11-positive leukemic cell lines K562 and CCRF-CEM are more sensitive to platinum derivatives, but not 5-fluorouracil compared to SLFN11-knockout cells." (PMID 34571887, 2021).